GFAP (glial fibrillary acidic protein)
Diseases named in the same sentence as GFAP in open-access papers (continued):
Sharing a sentence is not in itself a finding about the gene and the disease.
cognitive decline (continued). "Future research should investigate whether fragmented GFAP in AD biofluids correlates with disease progression or cognitive decline, which could establish GFAP-BDPs as biomarkers for astrocyte dysfunction in AD." (PMID 40690136, 2025). "Higher levels of blood-based neurodegenerative biomarkers (ie, t-tau, NfL, and GFAP) were associated with a faster rate of cognitive decline among APOE4 carriers than noncarriers." (PMID 40332937, 2025). "Notably, GFAP levels were higher in retired boxers, with a correlation with decreased volumes of multiple brain structures and cognitive decline over time." (PMID 38397046, 2024). "Elevated plasma GFAP levels correlate with amyloid pathology and cognitive decline." (PMID 38994939, 2024). "However, GFAP was found to be a top predictor across all age strata in cognitive decline models and especially for Aβ+s." (PMID 39291164, 2024). "Notably, the finding that GFAP levels in the blood are most strongly related to cognitive decline among amyloid-positive individuals appears to be strongly supported by our data in the brain." (PMID 39580758, 2024). "Finally, we sought to characterize the interaction between brain GFAP expression and amyloid on components of AD downstream of amyloid deposition, including tau pathology and cognitive decline." (PMID 39580758, 2024). "Similarly, in male PD group, the baseline GFAP interaction with time seemed to have a more remarkable and comprehensive predictive effect on cognitive decline, mainly in episodic memory, visuospatial ability, language and processing speed/attention." (PMID 37475029, 2023). "Likewise, it will be important for future studies to test how GFAP changes over disease course and if it predicts future cognitive decline in LBSD." (PMID 37000892, 2023). "Emerging evidence from studies with blood biomarkers seems to indicate that GFAP might be a strong biomarker candidate for objective cognitive decline among individuals with SCD or cognitively normal older people." (PMID 37951931, 2023). "GFAP and NfL could be biomarkers of cognitive decline in PD, but it should be considered that NfL can also reflect motor symptoms." (PMID 37480401, 2023). "Several previous reports have demonstrated age associated with changes in plasma NfL and GFAP, although age effect on NfL concentration does not predict cognitive decline or AD." (PMID 37924152, 2023). "For example, recent evidence pointed to GFAP as an important biomarker for progressive MS, as increased GFAP levels could help to delineate the transition into the late phase of subclinical cognitive decline, preceding progressive MS." (PMID 35625814, 2022). "Plasma GFAP levels have also been shown to be associated with cognitive decline in a cohort combining individuals with and without cognitive impairment." (PMID 34859598, 2022). "When performing sensitivity analyses for cell type fraction leveraging the abundance of cell-specific single gene markers (e.g., ENO2 for neurons, GFAP for astrocytes, CD68 for microglia), PLD3 associations with β-amyloid and cognitive decline remained significant (p<0.05)." (PMID 33830999, 2021). "Markers of neuroinflammation (e.g., CD74, GFAP) have been reported to increase in the hippocampus with age but the manner in which these changes may contribute to cognitive decline with normative aging remain to be determined." (PMID 21989322, 2011). "In addition, we found that higher baseline plasma biomarkers (e.g., GFAP, NfL, and p-tau181) were associated with brain atrophy but not with cognitive decline." (PMID 40877465, 2026). "While plasma GFAP levels correlate strongly with Aβ pathology and cognitive decline, their relationship with tau pathology remains unclear, raising questions about whether GFAP elevation occurs independently of neurodegeneration or as part of a compensatory astrocytic response." (PMID 40690136, 2025). "GFAP and NfL were also associated with cognitive decline in the HRS, but not in LASI-DAD." (PMID 40838581, 2025).
cognitive decline (continued). "Thus, even though NfL and GFAP are biomarkers non-specific to AD, the cognitive decline predicted by both can be explained by their association with neurodegeneration and neuroinflammation, respectively." (PMID 38755703, 2024). "In addition to demonstrating that these plasma biomarkers are associated with future neurodegenerative and cognitive trajectories, we show that the extent to which GFAP and pTau-181 predict brain atrophy and cognitive decline depends on the burden of brain amyloid." (PMID 38689358, 2024). "Similarly, when testing if amyloid and GFAP levels interacted on longitudinal cognition, we observed a significant interaction in the dlPFC between GFAP protein levels and amyloid status, such that high GFAP related to a faster rate of cognitive decline in amyloid-positive individuals." (PMID 39580758, 2024). "Moreover, both serum NfL and serum GFAP levels are associated with cognitive functioning in RVCL-S, showing the potential of these neuronal injury and astrogliosis biomarkers for monitoring disease progression and cognitive decline for SVD." (PMID 38581544, 2024). "Moreover, the absolute baseline plasma levels of pTau181 and GFAP reflect cognitive decline over the next 4 years, providing prognostic information that may have utility in both clinical practice and clinical trial populations." (PMID 36937522, 2023). "We next investigated whether plasma GFAP could predict more rapid cognitive decline in PD." (PMID 36759508, 2023). "A combination of demographic factors with APOE4 status and blood biomarkers, such as GFAP and NfL, might offer a reliable differentiation between healthy controls and patients with an objective cognitive decline, particularly between healthy controls and patients with AD." (PMID 36072480, 2022). "Our work also revealed that while astrocyte activation increases throughout the hippocampus with advanced aging, no cognitive decline-associated differences in GFAP protein content or numbers of GFAP+ astrocytes are apparent between aged intact and aged impaired rats." (PMID 21989322, 2011). "Glial fibrillary acidic protein (GFAP), a marker of astroglial activation, predicts cognitive decline in C9orf72 carriers." (PMID 40283201, 2025). "Plasma p-tau181 reduces tau-PET screening failures by ~50%, while plasma glial fibrillary acidic protein (GFAP) mediates Aβ-PET effects on tau-PET burden and cognitive decline." (PMID 40606501, 2025). "Therefore, the increase in TNF-α levels induced by GFAP-Cre-mediated hepcidin depletion may account for the decrease in the proliferation of hippocampal NSCs, thus contributing to abnormal hippocampal development and cognitive decline in mice." (PMID 38195497, 2024). "Cognitive decline was significantly predicted in MCI by baseline plasma NfL (β=-0.55), GFAP (β=-0.36), hippocampal volume (β = 0.44), centiloid (β=-0.38), and tau-SUVR (β=-0.66) (all p < 0.05)." (PMID 38755703, 2024). "This study suggests that plasma GFAP and NfL levels, and neuroimaging biomarkers (i.e., centiloid, tau-SUVR, hippocampal volume) can predict cognitive decline in MCI subjects." (PMID 38755703, 2024). "We specifically identified plasma GFAP and NFL as predictors of cognitive decline and progression during the early AD stage in CU and MCI participants." (PMID 38994939, 2024). "In line with the observed cognitive decline, significant increases in IBA1 and GFAP immunofluorescent intensity, as well as IL-1β expression were also observed in the APN-KO mice." (PMID 39415089, 2024). "Background: this prospective observational study aims to assess serum levels of glial fibrillary acidic protein (GFAP), s100b, and total Tau in long-COVID patients, exploring correlations with symptoms, cognitive decline, mental health, and quality of life." (PMID 38541055, 2024). "In conclusion, the finding that baseline levels of biomarkers such as GFAP, UCH-L1, Tau, and NF-L can predict cognitive decline in patients with TBIs of varying severity." (PMID 38397046, 2024).
cognitive decline (continued). "It is worth noting that the longitudinal increase in plasma biomarkers (e.g., GFAP) was correlated with accelerated cognitive decline in processing speed and visual attention but not with brain atrophy." (PMID 40877465, 2026). "Specifically, compared with noncarriers, APOE4 carriers had annual rates of cognitive decline per 1–log10 unit higher levels in t-tau and GFAP that were accelerated by a β (SD) of −0.03 (0.02) (P = .046) and −0.07 (0.03) (P = .02), respectively." (PMID 40332937, 2025). "An excellent diagnostic accuracy of plasma biomarkers of Aβ and tau obtained with ultrasensitive techniques has recently been demonstrated, and other potential blood biomarkers, including NfL, GFAP, BDNF are of particular interest in the early stages of cognitive decline." (PMID 40400914, 2025). "In HRS, higher GFAP levels (OR = 1.19) and a higher factor score (OR = 1.19) were related to an increased likelihood of cognitive decline compared to no cognitive change in HRS." (PMID 40838581, 2025). "Furthermore, several prospective studies have demonstrated the potential predictive value of NfL and GFAP for the progression of CSVD neuroimaging markers and clinical manifestations, especially cognitive decline." (PMID 38539657, 2024). "Among cognitively unimpaired older adults, plasma biomarkers of AD pathology (pTau-181) and astrogliosis (GFAP), but not neuronal injury (NfL), serve as markers of future brain atrophy and cognitive decline." (PMID 38689358, 2024). "The plasma concentrations of Tau, GFAP, NF-L, and UCHL1 correlated with cognitive decline." (PMID 37686075, 2023). "Unfortunately, they did not confirm GFAP as a prognostic biomarker for future cognitive decline and CSF biomarker changes in PD." (PMID 37475029, 2023). "Indeed, the NTK markers αSyn, GFAP, NfL, S100, sTREM2, YKL40 as well as p-tau and the combinations p-tau/a-beta and t-tau/a-beta, predicted cognitive decline in PD during follow-up, revealed by correlating the CSF levels with the cognitive measurements." (PMID 34618817, 2021). "For GFAP, as with the other 2 biomarkers, the rate of cognitive decline was not accelerated in non–APOE4 carriers, but it was accelerated among APOE4 carriers per unit increase in GFAP, with an estimate (SD) of −0.12 (0.03) per year (P < .001) (eTable 2 in Supplement 1)." (PMID 40332937, 2025). "We therefore propose that, in the oldest old, elevated plasma GFAP may reflect age‐related rather than AD‐related cognitive decline." (PMID 41416584, 2025). "In addition to amyloid and tau biomarkers, glial fibrillary acidic protein (GFAP) serves as a marker of astrocytic activation and neuroinflammation, processes that occur early in AD pathophysiology and may precede overt cognitive decline." (PMID 41287525, 2025). "Plasma GFAP can be used as an accessible biomarker to monitor motor, non-motor, and cognitive performance and as an early potential biomarker to predict longitudinal motor and non-motor symptoms deterioration, cognitive decline, and postural instability in PD." (PMID 37932720, 2023). "This is in contrast to other, longitudinal studies, which have found that plasma (and CSF) GFAP could predict global cognitive decline even though plasma GFAP was not always measured longitudinally." (PMID 35922871, 2022). "The current study demonstrates that plasma biomarkers of AD pathology (pTau-181) and astrogliosis (GFAP), but not neuronal injury (NfL), may serve as markers of future brain atrophy and cognitive decline among cognitively unimpaired older adults in the community." (PMID 38689358, 2024). "Similarly in this population, elevated GFAP within 12 months of TBI predicted poor cognitive outcome (perceptual reasoning) following complicated mild and severe TBI, and elevated NfL and tau predicted cognitive decline (perceptual reasoning, executive functioning) following uncomplicated mild TBI." (PMID 38292036, 2023).
cognitive decline (continued). "Notably, when considering both baseline neurodegenerative serum biomarkers and the APOE4 carrier status, the difference in cognitive decline between APOE4 carriers and noncarriers increased with higher levels of t-tau, NfL, or GFAP." (PMID 40332937, 2025).
ischemic stroke (131 papers, 2011 to 2026). A stroke disorder caused by obstruction of blood flow to the brain, due to thrombotic (local blood clot formation) or embolic (due to a blood clot or other material traveling from another site) event. "Recently, a systematic review confirmed the high diagnostic accuracy of blood GFAP levels as a discriminative test for cerebral hemorrhage and ischemic stroke." (PMID 40066310, 2025). "Several previous studies showed that serum biomarkers such as S100B, NfL, CAF, and Glial fibrillary acidic protein (GFAP) were associated with the prognosis of ischemic stroke, ICH and traumatic brain injury." (PMID 36068493, 2022). "Reduced expression of GFAP in the peri-infarct cortex was associated with increased axonal sprouting and better functional recovery 7 days after ischemic stroke." (PMID 34379293, 2021). "After ischemic stroke astrocytes become activated and increase their expression of GFAP, a hallmark of reactive astrogliosis." (PMID 28325900, 2017). "Plasma GFAP is a protein constituent of astrocyte intermediate filaments and elevated GFAP concentrations are thought to reflect astrocyte activation and reactive gliosis linked with several CNS disorders e.g. neurotrauma, ischemic stroke or neurodegenerative diseases." (PMID 38762725, 2024). "Numerous findings have suggested that the more immediate structural damage to the artery and blood-brain barrier caused by hemorrhage in comparison with ischemic stroke renders the subsequent surge in GFAP levels a reliable indicator of hemorrhage specifically." (PMID 30190542, 2018). "Additionally, ischemic stroke caused a significant increase in GFAP staining intensity (p < 0.001)." (PMID 41373489, 2025). "GFAP may also increase in ischemic stroke associated with hemorrhagic transformation." (PMID 38581002, 2024). "Researchers have identified a positive correlation between increasing GFAP and functional deficits post ischemic stroke." (PMID 41306424, 2025). "In summary, the use of blood biomarkers, particularly GFAP, holds promise for the diagnosis and differentiation of ischemic stroke and cerebral hemorrhage." (PMID 40066310, 2025). "In a single-center prospective study with 286 ischemic stroke patients, multivariate analysis showed that increased GFAP concentrations at admission independently predicted unfavorable outcome during the 1-year follow-up." (PMID 40421099, 2025). "For example, GFAP and D-dimer can be used to differentiate between hemorrhagic and ischemic strokes or to indicate a cardioembolic source, respectively." (PMID 40949500, 2025). "GFAP achieved an accuracy of 94.2% for differentiating hemorrhagic from ischemic stroke, with a cut-off value of 77.15 pg/mL." (PMID 40649119, 2025). "It is therefore relevant that the LVOne test is currently undergoing prospective validation of capillary testing for GFAP and D-Dimer for the triaging of ischaemic stroke due to large vessel occlusion (ISRCTN12414986)." (PMID 40650780, 2025). "Ischemic stroke leads to increased blood–brain barrier permeability and the release of neuronal and axonal injury biomarkers, such as GFAP, neurofilament light chain protein (NFL), and S100 proteins." (PMID 40066310, 2025). "Several studies support the application of GFAP as a biomarker in differentiating ischemic stroke (IS) from ICH." (PMID 40949500, 2025). "GFAP, an intrinsic component of the neural framework, rises to prominence following central nervous system damage, including ischemic strokes." (PMID 40026944, 2025). "In healthy individuals, serum GFAP levels remain undetectable unless necrosis and cell breakdown occur, as seen in cases of ischemic stroke or intracranial hemorrhage." (PMID 40142325, 2025). "Multicenter studies have demonstrated that GFAP is released more gradually in ischemic stroke compared to its rapid increase in hemorrhagic stroke." (PMID 40142325, 2025).